AKR1B10 (aldo-keto reductase family 1 member B10)
Diseases named in the same sentence as AKR1B10 in open-access papers (continued):
Sharing a sentence is not in itself a finding about the gene and the disease.
Uterine leiomyoma (1 paper, 2022). The presence of a leiomyoma of the uterus. "We and others have shown that overexpression of AKR1B10 can function as a biomarker for FH-deficiency and NRF2 activation in uterine leiomyomas and renal cell cancer." (PMID 36068196, 2022). "In this study, we present a novel uterine leiomyoma subtype that is FH-proficient but displays AKR1B10 protein expression." (PMID 36068196, 2022).
cancer (102 papers, 2007 to 2026). A tumor composed of atypical neoplastic, often pleomorphic cells that invade other tissues. "Further research has associated AKR1B10 expression levels with acquired chemoresistance and survival outcomes in various cancers, uncovering the mechanisms involved 16,32." (PMID 39744163, 2025). "This pan-cancer analysis suggested that AKR1B10 also associated with poor prognosis in GBM, SKCM, STAD, PAAD, KIRC, KIRP, and TGCT, but with favored prognosis in ACC and CESC." (PMID 39712017, 2024). "While the methylation analysis showed that AKR1B10 expression was significantly negatively associated with DNA methylation in 12 types of cancer." (PMID 39712017, 2024). "Our analysis showed AKR1B10 expression was significantly associated with TMB in 12 types of cancers, with HNSC correlation coefficient larger than 0.2, THYM, SKCM, ESCA and READ correlation coefficient smaller than -0.2." (PMID 39712017, 2024). "Overexpression of AKR1B10 was seen in cancers of the lungs and liver associated with a less aggressive clinical course, whereas AKR1B1 was more widely overexpressed in several cancers and associated with shortened patient survival." (PMID 39055885, 2024). "Previous studies have indicated that unusually low levels of AKR1B10 in the GI tract are closely associated with cancer development." (PMID 39737179, 2024). "Aldo–keto reductase family 1 member B10 (AKR1B10), a tumor-associated enzyme, exhibits abnormal expression in various cancers." (PMID 38802416, 2024). "AKR1B10 is an extensively studied enzyme with high retinaldehyde reductase activity linked to the development of various cancers." (PMID 38086955, 2023). "MT1M, SLCO1B3, SPINK1, and AKR1B10 were cancer-related genes that were associated with different human diseases, especially in HCC." (PMID 36246599, 2022). "AKR1B1 and AKR1B10 have been associated with different cancers; however, their roles differ among cancer types." (PMID 35159076, 2022). "AKR1B10 has been reported to be associated with cancer development, progression, and treatment through several mechanisms, such as detoxification of RCS or regulation of lipid synthesis." (PMID 36661656, 2022). "Recent studies have implicated AKR1B10 in tumor growth and metastasis, and reported aberrant expression levels in various cancers." (PMID 32615540, 2020). "Aside from being associated with lung carcinogenesis, AKR1B10 expression has also been linked to the development of several additional types of cancers." (PMID 32097409, 2020). "TFF1, THY1, and AKR1B10 are associated with various cancers and have been implicated as biomarker candidates." (PMID 29713252, 2018). "The association of AKR1B10 expression with clinical progression of cancers was evaluated by Kaplan-Meier analysis; the potential role of AKR1B10 in tumor microenvironment (TME) and immune-related gene expression were analyzed by PURITY, ESTIMATE, TIMER and CIBERSORT algorithms." (PMID 39712017, 2024). "In this study, we compared the expression of AKR1B10 in multiple types of normal tissues and cancers, evaluated the relationship of AKR1B10 expression with DNA mutation, DNA methylation, cancer clinicopathology, cancer microenvironment and immune cell infiltration, and survivals in pan-cancers." (PMID 39712017, 2024). "Interestingly, our data showed for the first time that AKR1B10 expression was significantly associated with DNA methylation in pan-cancers." (PMID 39712017, 2024). "Since HCCFA, MK204, and oleanolic acid are commercially available, they can be used for elucidating the mechanisms underlying tumorigenesis of AKR1B10-overexpressing cancers and chemotherapy resistance, which would precede AKR1B10-based therapies in clinical cancer management." (PMID 34063865, 2021).
cancer (continued). "The cause of opposite pattern of expression in cancers inside or outside the digestive tracts might be related to unknown functions of AKR1B10 in different tissues." (PMID 26949513, 2016). "AKR1B10 also reduces RA levels and RA has been implicated in inhibiting cancer cell proliferation." (PMID 26516929, 2015). "Whether the 14-3-3ε/β-catenin/AKR1B10 axis is involved in the tumor microenvironment or in “educating” cancer associated stromal cells by affecting lipid metabolism needs to be further investigated." (PMID 26516929, 2015). "Further, the expression of this enzyme is elevated in cancer cells that are resistant to clinical anticancer drugs such as ethoxyquin, doxorubicin, and lipopolysaccharide, suggesting a potential association between the AKR1B10 expression and resistance to chemotherapy." (PMID 39737179, 2024). "In addition, AKR1B10 is increased and implicated in the acquisition of anti-cancer drug resistance." (PMID 34063865, 2021). "Thus, 14-3-3ε may synergize with AKR1B10 to promote tumor growth, not only by autocrine regulation in cancer cells, but also in regulating tumor associated stromal cells in a paracrine manner." (PMID 26516929, 2015). "Our findings reveal a novel regulatory axis where LDHA is activated by AKR1B10, highlighting critical enzyme–enzyme crosstalk in cancer metabolism." (PMID 41454479, 2026). "As previously reported, EPA is an inhibitor of AKR1B10, suppressing its secretion and enzymatic activity in multiple cancer types." (PMID 41454479, 2026). "The quest for effective AKR1B10 inhibitors has the potential to enhance the efficacy of chemotherapy and open up new prospects for clinical cancer treatment." (PMID 39737179, 2024). "A pan-cancer analysis demonstrated elevated expression of AKR1B10 across various cancers, including CHOL, KIRP, LIHC, LUAD, LUSC, and UCEC." (PMID 38931461, 2024). "Our study provides a landscape of AKR1B10 in pan-cancers and suggests a potential role of AKR1B10 in tumor microenvironment remodeling." (PMID 39712017, 2024). "This study provided a landscape of AKR1B10 in pan-cancers, including its expression and potential roles in TME, tumor immunity, and survival." (PMID 39712017, 2024). "Analysis of the Oncomine cancer gene expression database revealed wide variations in the expression of AKR1B1 and AKR1B10 in different cancer types." (PMID 39055885, 2024). "This study is designed to understand how sublethal doses of chemotherapy drugs like taxol and doxorubicin lead to increased cancer cell migration, invasion, metastasis, and the consequent upregulation of AKR1B10." (PMID 39001490, 2024). "Our study for the first time presents a landscape of AKR1B10 in pan-cancers and discusses the context-dependent function of AKR1B10 in cancers." (PMID 39712017, 2024). "The development of highly selective AKR1B10 inhibitors offers promising prospects for improving tumor treatment and survival rates for patients with cancer." (PMID 39737179, 2024). "Subsequently, we evaluated the prognostic value of AKR1B10 in multiple types of cancers through Kaplan-Meier analysis." (PMID 39712017, 2024). "We found that AKR1B10 expression significantly correlated with HRD in 9 types of cancer, with ESCA, KIRP and PCPG correlation coefficient lager than 0.2." (PMID 39712017, 2024). "Further studies revealed that AKR1B10 was most remarkably and positively enriched with multiple metabolism processes, including drugs, hormones, saccharides, and amino acids in pan-cancer." (PMID 39712017, 2024).
cancer (continued). "The AKR1B10 expression in cancers and its value in disease progression was bidirectional and functionally enriched in metabolism in pan-cancers." (PMID 39712017, 2024). "The function of AKR1B10 in cancer have attracted the attention of scientists, the role of AKR1B10 in TME remains elusive." (PMID 39712017, 2024). "Aldo-keto reductase 1B10 (AKR1B10) is a multifunctional enzyme, which is important in cancer development and progression, but the landscape of AKR1B10 in pan-cancers and in tumor microenvironment is unclear." (PMID 39712017, 2024). "The AKR1B10 (Aldo-Keto Reductase Family 1, Member B10) reduces aromatic and aliphatic aldehyde substrates and was shown to promote cancer cell survival." (PMID 36817482, 2023). "Using multilevel TCGA and CCLE data, we showed that AKR1B10 expression is a robust biomarker for NRF2 activation across cancers." (PMID 36068196, 2022). "In the present meta-analysis, summary results without significant heterogeneity showed that high expression of AKR1B10 in malignant tumor tissue was significantly correlated with better OS and RFS in HCC patients after hepatectomy." (PMID 36584078, 2022). "An increasing number of studies have shown that AKR1B10 elevation is responsible for certain cancers." (PMID 36476503, 2022). "AKR1B10 possesses potentials in cancer development and progression, which has emerged as a diagnostic target for tumors." (PMID 36028503, 2022). "Fifth, AKR1B10 also functions as an important regulator of de novo fatty acid/lipid synthesis, which is essential for cancer cell growth and division." (PMID 36661656, 2022). "For example, AKR1B10 is significantly upregulated in cancers of the breast, lungs, and liver, and AKR1B10 overexpression facilitates the malignant phenotypes of these cancers." (PMID 36476503, 2022). "Increasing evidence unveiled that AKR1B10 was induced in many cancer tissues and shared correlation with tumor progression and some noncanceraous diseases." (PMID 36028503, 2022). "AKR1B10 plays a central role in cancer lipid metabolism by governing the synthesis of lipids through stabilizing acetyl coenzyme-A carboxylase α." (PMID 34419144, 2021). "AKR1B10 is induced in various types of cancer tissues and down-regulated in gastrointestinal cancers." (PMID 34063865, 2021). "Herein, we reviewed the literature on the roles of AKR1B10 in a healthy gastrointestinal tract, the development and progression of cancers and acquired chemoresistance, in addition to its gene regulation, functions, and inhibitors." (PMID 34063865, 2021). "Human aldo-keto reductase 1B10 (AKR1B10) is overexpressed in many cancer types and is involved in chemoresistance." (PMID 34940623, 2021). "For a novel target that is conductive to prevent and treat cancer, increasingly attention has been paid on inhibitors of AKR1B10." (PMID 34552036, 2021). "Studies with chemoresistant cells suggest that the role of AKR1B10 in chemoresistance development is dependent on the anti-cancer drugs or cancer cells used." (PMID 34063865, 2021). "Consistently, AKR1B10 overexpression induced cancer cell aggressiveness, whereas suppression of AKR1B10 by siRNA or its small molecular inhibitor, oleanolic acid, reversed the CBX7 deficiency-induced cellular effects." (PMID 34035231, 2021). "Previously, AKR1B10 was proposed to be a biomarker for liver, lung, and other cancers, and shown to act as a carbonyl reductase on the chemotherapeutic daunorubicin." (PMID 33889302, 2021). "IRAK1 enhances cancer stemness and weakens the sensitivity to doxorubicin and sorafenib using the AP-1/AKR1B10 axis in HCC." (PMID 34621787, 2021). "Aldo-keto reductase family 1 member B10 (AKR1B10) is indispensable to cancer development and progression, which has served as a diagnostic biomarker for tumors." (PMID 34552036, 2021).
cancer (continued). "In this review, we summarize recent progress towards understanding the gene regulation of AKR1B10 and its functions in gastrointestinal physiology, the pathogenesis of several cancers and skin diseases, and acquired drug resistance." (PMID 34063865, 2021). "ROC curve analysis indicated that AKR1B10 gene expression value was able to correctly identify non-cancer tissue (AUC 0.76, P<0.0001), with relatively high specificity (98.31%)." (PMID 32097409, 2020). "For this reason, as a future scope of research, we aim to study the mechanisms by which BTK inhibitors target AKR1C3 and AKR1B10 and modulate cell proliferation for potential applications in cancer treatment." (PMID 33322571, 2020). "Significant correlation has been identified between overexpression of AKR1B10 and the proliferation of different types of cancer cells." (PMID 32850805, 2020). "The human orthologue of Akr1b8, AKR1B10, has been reported to be upregulated in a number of cancer types including breast cancer, but the clinical and metabolic consequences of this altered expression have not been investigated." (PMID 31221959, 2019). "Results from several studies support the use of inhibitors as anti-proliferative agents against AKR1B10-overexpressing cancers like HCC and as adjuvant drugs for overcoming chemoresistance in HCC." (PMID 30959792, 2019). "Further, inhibition of AKR1B10 in HCC will allow for a better response to chemoresistance because of its ability to metabolize a wide range of cancer drug therapies." (PMID 30959792, 2019). "AKR1B10 overexpression has been reported in several types of cancer, including lung, pancreatic and hepatocellular tumors." (PMID 29532688, 2018). "Accumulating evidence reveals that AKR1B10 functions as a pivotal promotor of human cancers in multiple tissues and organs, including breast, lung, liver, endometrium and gastrointestinal mucosa." (PMID 30038373, 2018). "AKR1B1’s homologue AKR1B10 is overexpressed in multiple cancer types, including malignancies of breast, prostate and lungs, and is deemed suitable as a target in cancer treatment." (PMID 29532688, 2018). "A series of pathways involving in tumorigenesis and progress were observed, including cellular aldehyde metabolic process, The oncogenetic functions of AKR1B10 have been reported in many other types of cancer by previous studies." (PMID 30038373, 2018). "Aldo-keto-reductase 1B10 (AKR1B10) is upregulated in various types of cancer and has been reported to promote carcinogenesis." (PMID 30469331, 2018). "Further studies on the gene regulation of AKR1B10 will reveal an internal mechanism about its role on the development and progression of cancers." (PMID 28402270, 2017). "In spite of these studies, however, very little studies were focus on the mechanism of the aberrantly overexpressed AR/AKR1B10 contribute to the development or progression of various types of cancers." (PMID 28978011, 2017).